KAT5 (lysine acetyltransferase 5)
Diseases named in the same sentence as KAT5 in open-access papers (continued):
Sharing a sentence is not in itself a finding about the gene and the disease.
tumor (continued). "However, TIME database analysis found that KAT5 was weakly correlated with tumor infiltrating lymphocytes." (PMID 37365518, 2023). "It is plausible that in ATC, miRNA is regulated by KAT5 and contributes to tumor progression." (PMID 37342240, 2022). "Hence, we proposed that ASP decreased expression of PD-L1 protein via inhibiting the epigenetic regulation by KAT5 and suppressed the PD-1/PD-L1 signaling to attenuate tumor growth." (PMID 35392432, 2022). "In addition to regulating the transcription of TWIST1, it has been reported that KAT5 increases the stability of c-Myc through acetylation of c-Myc, thereby promoting tumor invasion and metastasis." (PMID 34650217, 2021). "Consequently, the inhibition of KAT5 can suppress tumor growth." (PMID 36986843, 2023). "Therefore, KAT5 is involved in several pivotal cellular physiological and pathological processes, including carcinogenesis and tumor progression, and could be a novel potential therapeutic target for ATC treatment." (PMID 37342240, 2022). "We first attempted to assay histone H4-Ac as a surrogate marker for KAT5 activity along with endogenous p27 and Ki67 levels by IHC in FFPE tumor samples and, also, by FACS analysis of freshly fixed and permeabilized samples." (PMID 40346033, 2025). "For our assays, we collected 10 tumors (3 LGG IDH1/2mut, 5 HGG tumors, and 2 HGG IDH1/2 mut) and performed KAT5 activity and protein synthesis assays (30 min treatment with O-propargyl-puromycin (OPP)) in match cohorts of tumor cells." (PMID 40346033, 2025). "Its catalytic component, Esa1 (the human homologue as lysine acetyltransferase 5 (TIP60/KAT5)), is involved in RNA transcription, circadian rhythms, DNA repair, and tumor progression." (PMID 39780291, 2025). "In terms of KAT5, SIRT4, SIRT6 and SIRT7, these four genes demonstrated higher expression in tumours than in adjacent tissues." (PMID 36308411, 2022). "KAT5 mediates PFKP acetylation, leading to its membrane translocation, subsequently activating PFK1 and increasing GLUT1 expression, thereby promoting glycolysis and tumour cell proliferation." (PMID 39778006, 2025). "KAT5 chromatin binding was assessed using CUT&TAG53 analysis for KAT5on and KAT5off tumor samples." (PMID 40346033, 2025). "The involvement of three enzymes, VRK1, Tip60/KAT5 and SIRT2, in the regulation of the level of acetylation of H4K16 opens up the possibility of its pharmacological manipulation by their combination, to promote the elimination of tumor cells." (PMID 36902348, 2023). "In KAT5-repressed cancer cells, the study investigators detected induction of IRF7 mediated by the intracellular pathogen sensing STING (HGNC: TMEM173), resulting in an inflammatory response and further tumor growth." (PMID 36979914, 2023). "Densitometry analysis showed that KAT6A, KAT6B and KAT7 significantly decreased in KIRC tumor tissues, but KAT5 in KIRC tumor tissues decreased to some extent, but the change was not significant." (PMID 37365518, 2023). "Finally, we assessed PCK1, c-Myc, Twist1, E-cadherin expression and KAT5 O-GlcNAcylation in 48 paired human HCC tissues and tumor-adjacent tissues." (PMID 34650217, 2021). "Here, we show that TIP60, also known as KAT5, a haplo-insufficient tumor suppressor, directly acetylates XPF at Lys911 following UV irradiation or treatment with mitomycin C and that this acetylation is required for XPF-ERCC1 complex assembly and subsequent activation." (PMID 32034146, 2020).
tumor (continued). "Finally, regardless of grade of tumor, KAT5 activity significantly correlates with protein translation rates in tumor cells, such that low KAT5 correspond to lower protein translation rates and vice versa." (PMID 40346033, 2025).
infection (10 papers, 2010 to 2025). The state of being infected such as from the introduction of a foreign agent such as serum, vaccine, antigenic substance or organism. "Further, inhibition of kinase activity of c-Abl brought about by Imatinib also resulted in a loss of phosphorylated tyrosine of KAT5 during infection." (PMID 29449840, 2018). "Interestingly, RAW264.7 macrophages transfected with c-Abl KD elucidate reduced c-Abl-KAT5 interaction during infection." (PMID 29449840, 2018). "In addition, KAT5 levels were unperturbed during infection but its phosphorylated tyrosines (pY) were significantly increased." (PMID 29449840, 2018). "NS1 interacts with cellular histone acetyltransferase KAT5, and there is a significant increase in the expression of KAT5, GTF3C4, and KAT2A during MVC infection." (PMID 40733601, 2025). "Furthermore, the low activity of MYC at the first infection stage affects the low expression of SLC25A6, which suffers from the repression of human miR1244-1, the transcriptional silence of DNA methylation (p-value = 1.14 × 10−2), and the acetylation by acetyltransferase protein KAT5." (PMID 30133498, 2018).
neurodegenerative disease (4 papers, 2020 to 2025). A disorder of the central nervous system characterized by gradual and progressive loss of neural tissue and neurologic function. "Thus, TIP60/KAT5 emerges as a key guardian of neuronal health by mitigating early imbalances in TIP60/KAT5 HAT/histone deacetylase (HDAC) activity observed in various neurodegenerative diseases." (PMID 41227365, 2025).
kidney disease (2 papers, 2020 to 2024). "Collectively, these findings highlight the potential of targeting DNA damage pathways, such as via restoring expression of repair factors like KAT5, ATR, FANCD2 and ERCC1 in kidney cells, as a therapeutic approach to slow down the progression of kidney disease in both tubular cells and podocytes." (PMID 38773208, 2024). "However, the association of KAT5 expression with DNA DSB levels and kidney disease progression has not been clarified." (PMID 32099032, 2020).
kidney (1 paper, 2024). "A recent study demonstrated that KAT5 meliorated ischemic acute kidney injury through epigenetic modulation of KCC3 expression." (PMID 38561411, 2024).
KAT5 also shares sentences with these, for which no sentence is quoted: Alzheimer disease (15 papers); colon carcinoma (12); breast tumor (4); ataxia telangiectasia (3); cervical cancer (3); cognitive disorder (3); gastric cancer (3); head and neck cancer (3); metastatic melanoma (3); neurological disorders (3); skin cancer (3); amyotrophic lateral sclerosis (2); B-cell lymphoma (2); brain tumor (2); Fanconi anemia (2); herpesvirus infection (2); influenza (2); mesothelioma (2); metabolic disease (2); Parkinson disease (2); Spinocerebellar ataxia 1 (2); teratoma (2); acute lymphoblastic leukemia (1); age (1); Allergy (1); asthma (1); Atrophy (1); autism (1); autoimmune disease (1); cardiac hypertrophy (1).
A further 49 diseases each share a sentence with KAT5 in 1 paper.